TNF (tumor necrosis factor)
Diseases named in the same sentence as TNF in open-access papers (continued):
Sharing a sentence is not in itself a finding about the gene and the disease.
Insulin resistance (continued). "TNFα is a potent inducer of the NF-κB pathway, leading to insulin resistance and an increased inflammatory state, which are chronically observed in obese subjects." (PMID 34542797, 2022). "Muscle fibers produce cytokines and other peptides such as interleukin-6, which affect the immune response by inhibiting the production of tumor necrosis factor-α and insulin resistance." (PMID 36684364, 2022). "Another mechanism involved in TNF-α induction of insulin resistance in peripheral tissues is the activation of nuclear factor-κB (NF-κB) and stimulation of the transcription of cytokines and adhesion molecules." (PMID 35008925, 2022). "When we analyzed the phosphoproteome by TNF-α-induced insulin resistance, it was found that two canonical pathways were upregulated and eight canonical pathways were downregulated." (PMID 35055191, 2022). "Our results suggest that IRW and IQW reduced the levels of glucose, HDL, and LDL, improved GLU tolerance and insulin resistance induced by the HF diet, and decreased the mRNA expression of TNF-α, IL-6, and IL-1β." (PMID 36232527, 2022). "TNF-α can affect the breakdown of fat particles and the level of fatty acids in the body, ultimately leading to insulin resistance." (PMID 35453397, 2022). "There were significant decreases in insulin resistance, hyperinsulinemia, hyperglycemia, dyslipidemia, TNF-α, and IL-6 and concomitant increases in adiponectin and β-cell function." (PMID 36297570, 2022). "Adipose tissues mainly produce inflammatory biomarkers such as TNF- α, and macrophages and other immune cells are partially responsible for insulin resistance." (PMID 35057501, 2022). "Chronic inflammation, involving high serum tumor necrosis factor α (TNF-α) concentrations, accompanies large subcutaneous and visceral adipocytes, and is associated with insulin resistance and T2D in both humans and rodents." (PMID 36091357, 2022). "When compared with untreated cells, we also found that DEX or TNF-α treatment of C2C12 cells induced insulin resistance, as demonstrated by the inactivation of mTOR, and reduced Dnmt1 expression and enhanced expression of miR-193b." (PMID 34913989, 2022). "TNFα also contributes to insulin resistance by inducing hepatic lipolysis, thus increasing FFA levels in the circulation." (PMID 35054972, 2022). "miR-15b was found to have a role in the inhibition of insulin resistance by decreased TNFα and SOCS3 signaling and increased IGFBP-3 levels, resulting in REC protection from hyperglycemia-induced apoptosis." (PMID 35586497, 2022). "The cell cycle control of the chromosomal replication pathway was the most downregulated canonical pathway in TNF-α-induced insulin resistance." (PMID 35055191, 2022). "Our observation is concomitant to previous studies where IL6 and TNFα were found to be elevated in patients with lipid abnormalities and insulin resistance." (PMID 35360165, 2022). "The presence of central obesity promotes inflammation which subsequently leads to insulin resistance and endothelial dysfunction as increased levels IL-6, TNF-α and C-reactive protein and decreased levels of adiponectin and interleukin-10 are observed." (PMID 35382771, 2022). "The acetic acid concentration was weakly negatively correlated with blood glucose indicators and insulin resistance, and negatively correlated with serum IL-6, TNF-α, and IFN-γ concentrations." (PMID 35745208, 2022). "Among inflammatory mediators, TNF-α and interleukin-1β (IL-1β) have been reported to mediate insulin resistance by IKKβ and JNK1-induced IRS-1 serine phosphorylation." (PMID 35327570, 2022). "Sambucus nigra L. fruit extract alleviated insulin resistance by suppressing the enhanced production of NO, TNF-α, IL-6, and PGE2, where the presence of cyanidin-based anthocyanins, flavan-3-ols, flavonols, and hydroxycinnamic acids were detected." (PMID 35057523, 2022). "In experimental animals, overexpression of tumor necrosis factor-α (TNFα) leads to insulin resistance." (PMID 36551210, 2022).
Insulin resistance (continued). "Third, as well as being an energy-storing organ, adipose tissue is the largest endocrine organ producing adiponectin, leptin, TNF-α, and IL-6, which leads to systemic inflammation and insulin resistance, thereby further exacerbating NAFLD." (PMID 35453642, 2022). "Among inflammatory markers, TNF-α is one of the most important inflammatory cytokines that is critically involved in the development of insulin resistance and pathogenesis of T2DM." (PMID 35318405, 2022). "Tumor necrosis factor inhibits skeletal myocyte differentiation, promotes muscle atrophy, and contributes to insulin resistance by impairing the insulin signaling pathway." (PMID 35463384, 2022). "Interleukin (IL)-1β plays a role in insulin resistance and sensitivity through tumor necrosis factor-independent and dependent pathways." (PMID 36618710, 2022). "Regular physical activity induces suppression of TNF-alpha and thereby offers protection against TNF-alpha-induced insulin resistance." (PMID 35053667, 2022). "In diabetic and insulin-resistant conditions, elevated levels of TNF, IL-6, and IL-8 have all been recorded." (PMID 35276979, 2022). "ATMs are remarkably increased in obese WAT, which produce large amounts of TNF-α to drive insulin resistance and interfere with hepatic glycolipid metabolism." (PMID 36091076, 2022). "Improvement in insulin resistance has been reported to be related to chronic inflammation which can be measured by c-reactive protein, interleukin-6, or TNF-alpha or oxidative stress." (PMID 35242882, 2022). "We used a combination of TNF-α, insulin, and glucose for insulin resistance, and BSA-palmitate to treat cultured primary hippocampal and cortical neurons." (PMID 33859286, 2021). "A TNF-α neutralizing antibody has also been used to ameliorate TNF-α induced insulin resistance in adipocytes." (PMID 34489979, 2021). "In obese subjects, there is an increased TNF-α production which plays an essential role in the development of insulin resistance and local adipose tissue and systemic inflammation." (PMID 34202323, 2021). "Attenuation of TNFα/IL-1β/CCL2-mediated inflammation in metabolic organs has been shown to improve insulin resistance, consistent with the observed reduction of fasting insulin and HOMA-IR in KrO-treated mice." (PMID 34444996, 2021). "Proinflammatory cytokines (TNF-α and IL-6) are involved in multiple metabolic pathways related to insulin resistance." (PMID 33917607, 2021). "Th evidence indicates that IKK and JNK are plausible mechanistic links between TNF-α and insulin resistance through the phosphorylation of IRS1 at the inhibitory moiety." (PMID 34073455, 2021). "TNF-α has been known to stimulate serine phosphorylation of insulin receptor substrate 1, resulting in insulin resistance." (PMID 33669954, 2021). "During diabetes, oxidative stress and proinflammatory cytokines (such as TNF-α and IL-1β) enhance phosphorylation of NF-κB and JNK, causing inflammation and insulin resistance." (PMID 34685668, 2021). "It is known that PP4R1 is one of the regulatory subunits of PP4, which has been considered as a critical regulator in TNF-α induced hepatic insulin resistance." (PMID 33750415, 2021). "High levels of circulating TNF-α are believed to lead to severe inflammatory response, metabolic alteration, and insulin resistance." (PMID 34975827, 2021). "Recent evidence suggests a positive relationship between inflammatory markers including IL-1β, IL-6, CRP and TNF-α and insulin resistance." (PMID 34078385, 2021). "Among cytokines, tumor necrosis factor-alpha (TNF-α) is verified to be the driver behind insulin resistance." (PMID 34717724, 2021). "As well, tumor necrosis factor alpha (TNFα) levels positively correlate with adiposity, BMI, insulin levels, and insulin resistance." (PMID 33994998, 2021). "Considering the direction of the regression line, we conclude that eHsp70 and TNF-α lead to the development of insulin resistance." (PMID 35050141, 2021).
Insulin resistance (continued). "In mature adipocytes, SIRT1 promotes fat mobilization through repression of PPARγ and protects cells from TNF-alpha-induced insulin resistance." (PMID 34863096, 2021). "The function of TNF-α in insulin resistance is realized by serine phosphorylation of insulin receptor substrate-1 and downregulation of insulin-sensitive glucose transport protein." (PMID 34637688, 2021). "It is well documented that TNF-α has a fundamental role in the development of insulin resistance and the pathogenesis of T2DM." (PMID 34652617, 2021). "VA treatment also showed decreased expression of two key inflammatory markers, TNFα and IL1β, in the intestine, but research is needed to understand the effect of VA on gut microbiota during insulin resistance and related mechanisms." (PMID 34946118, 2021). "The peptic bee pollen polysaccharide (RBPP-P) of Rosa rugosa shows a regulatory effect toward certain pro-inflammatory cytokines that raise insulin resistance, e.g. TNF-α and IL-6." (PMID 35047540, 2021). "The second goal of this study was to investigate the relationship between miRNAs and inflammatory factors such as TNF-α, IL-6 and insulin resistance to understand the role of miRNAs in the development of T2DM." (PMID 34077450, 2021). "TNF-α is involved in insulin resistance in obese animals and can damage insulin function, which down-regulates glucose transporter-4 (GLUT4) expression and action during glucose metabolism and enhances lipolysis." (PMID 34443619, 2021). "A high abundance of TNFα induced insulin resistance leading to glucose intolerance and cognitive dysfunction, as we observed in the HFS group." (PMID 35010897, 2021). "Tumor necrosis factor (TNF) is a multifunctional cytokine that can directly damage islet β-cells and induce insulin resistance by inhibiting the transduction of insulin signals." (PMID 34824300, 2021). "TNFα directly affects insulin signalling and, thus, has a role in the development of insulin resistance and obesity." (PMID 34572059, 2021). "Insulin stimulation did not increase glucose uptake in 3T3-L1 cells after TNFα treatment, while DHM prevented the TNFα-induced insulin resistance." (PMID 34650665, 2021). "TNF-α is an important mediator for insulin resistance in obese subjects, and it mainly induces insulin resistance by weakening the insulin receptor signal transduction." (PMID 34574191, 2021). "Other factors such as “increased levels of serum cortisol”, “Tumor necrosis factor α (TNF α, ILs e.g., IL-6), can interrupt the insulin signaling pathway and can lead to insulin resistance during normal pregnancy”." (PMID 34055923, 2021). "AQP7 is downregulated in terms of insulin resistance according to the in vitro studies on mice adipocytes where insulin resistance was induced by dexamethasone or TNFα." (PMID 34069293, 2021). "Curcuminoids have been shown to improve insulin resistance, decrease glucose and insulin levels, increase adiponectin release, and reduce the levels of leptin, resistin, interleukin (IL)-6 IL-1β, and tumor necrosis factor-α in patients with T2DM." (PMID 34012421, 2021). "It has been indicated that inflammatory mediators such as TNF-α and IL-6 are increased with insulin resistance and play an important role in deregulating glucose homeostasis in type 2 DM." (PMID 33968046, 2021). "TNF-α shows a significant effect on the variability of the insulin resistance index even in healthy euglycemic subjects." (PMID 35050141, 2021). "Excess adipogenesis eventually results in adipocytic abnormalities, dyslipidemia, and insulin resistance, due to increased production of angiotensin 2, resistin, TNF-α, interleukin 6, interleukin 1-β, and free fatty acids." (PMID 34299261, 2021). "Ablation of TIMP-3 in mouse enhanced inflammation by dysregulating the activity of ADAM17 (a TIMP-3 target metalloproteinase) and the subsequent release of its substrate TNF, thus promoting insulin resistance and hepatosteatosis." (PMID 33673623, 2021).
Insulin resistance (continued). "It has been determined to be involved in the regulation of TNF-α-induced hepatic insulin resistance and gluconeogenesis." (PMID 33750415, 2021). "M1 macrophages induce an inflammatory and insulin resistance state through the inhibition of insulin signaling, indirectly produced by TNF-α, IL-6, and IL-1β, while M2 macrophages protect against insulin resistance by an IL-10-dependent mechanism." (PMID 34944461, 2021). "Our data reveal that TNFα inhibits fatty acid and lipid metabolism, likely contributing to the accumulation of FFAs, which further contribute to insulin resistance." (PMID 34576943, 2021). "PP4R1 has been determined to be involved in the regulation of TNF-α-induced hepatic insulin resistance." (PMID 33750415, 2021). "Inflammatory cytokines such as tumor necrosis factor-α, interleukin (IL)-1β and IL-6 activate several inflammatory signaling pathways that promote insulin resistance." (PMID 34887771, 2021). "Peripheral insulin resistance and elevated plasma glucose and insulin levels are correlated with TNF-alpha concentration prior to the onset of T2DM." (PMID 34725640, 2021). "Others have shown that a very similar infusion of non-esterified fatty acids and insulin in lean research participants can result in insulin resistance and elevated TNF-alpha, although circulating cytokines were studied only after 48 hours." (PMID 33764994, 2021). "Insulin resistance has been widely recorded in malignant tumors contributing to cancer cachexia due to chronic exposure to pro-inflammatory cytokines, such as TNF-a, IL-6, and insulin growth factor binding protein." (PMID 33916252, 2021). "When U73122 blocked the PLC-IP3 receptor pathway, the ability of DHM to improve TNFα-induced insulin resistance disappeared, as shown by the glucose uptake assay." (PMID 34650665, 2021). "Skeletal muscles are responsible for the majority of postprandial blood glucose uptake and the TNF-α inflammatory axis adversely impairs the utility of glucose, resulting in hyperglycemia and insulin resistance." (PMID 34073455, 2021). "TNF-α was reported to be high in the adipose tissue of obese individuals, and its level was correlated positively with insulin resistance as it interferes with the insulin signalling transduction via serine-phosphorylation of IRS-1." (PMID 33557218, 2021). "TNF-α promotes insulin resistance by directly suppressing activities of insulin-induced insulin receptor substrate-1 and peroxisome proliferator-activated receptor gamma (PPAR-γ)." (PMID 35056068, 2021). "The rise in plasma TNFα may have served to preferentially induce the expression of the Ceacam1-4L variant through activating NF-κB in the anti-inflammatory M2 macrophages of VECadherin+Cc1fl/fl to enhance innate immunity and limit systemic inflammation that would otherwise drive insulin resistance." (PMID 34440862, 2021). "The downstream effectors and molecular consequences of the TNFα signaling pathway, and their influence in the development of insulin resistance, are well-characterized in the context of the adipose tissue." (PMID 34576943, 2021). "Adipocyte hypertrophy and adipocytokines, such as leptin and TNF-α, are considered to be key pathological contributors to insulin resistance." (PMID 35004802, 2021). "On the other hand, H2S plays a vital role in adipocyte insulin resistance mediated by tumor necrosis factor-α (TNF-α)." (PMID 34335475, 2021). "High blood levels of leptin play a major role in insulin resistance by inducing the production of IL-6 and TNF-α." (PMID 34069933, 2021). "Diabetes (DM) is one of the chronic diseases that develop due to severe inflammation and manifests in an increase in pro-inflammatory cytokines and chemotaxis mediated by B and T lymphocytes, such as IL-1β and TNF-α, leading to insulin resistance." (PMID 35047540, 2021).
Insulin resistance (continued). "According to literature data, increased amount of TNFα indicates macrophage-induced insulin resistance of the skeletal muscle, cerebral insulin resistance in Alzheimer’s disease and it inhibits the effect of insulin on glucose uptake and storage." (PMID 34572059, 2021). "TNF-α exacerbates hepatic insulin resistance, resulting in increased FFA synthesis and decreased FFA oxidation, thereby promoting hepatic steatosis." (PMID 34829740, 2021). "Galectin 2 is suspected of having an impact on macrophages M1 and M2 by its polarization and releasing interleukin 6 (IL-6) and TNF-α, which generates insulin resistance." (PMID 34769010, 2021). "Studies on obese patients have outlined that insulin resistance and related disorders are characterized by a cytokine imbalance, with high levels of TNFα, IL-6, IL-1β, CRP, and NF-κB." (PMID 33995414, 2021). "In particular, TNF-α aggravates insulin resistance via activation of c-Jun kinase, which inhibits the phosphorylation of insulin receptor substrate-1 and hence blocks insulin signaling, resulting in exacerbation of the inflammatory response." (PMID 34366841, 2021). "The TNF in CD4 T cells was unchanged relative to the control group in the insulin resistance study, whereas the TNF from CD8+ T cells was more abundant in the BpOmpW group compared to control cells (p = 0.012)." (PMID 34966388, 2021). "TNF-α is one of the most important proinflammatory mediators and a key factor in insulin resistance, the evidence for which was well summarized in a classic review." (PMID 33953784, 2021). "A 1993 article first described the relationship between tumor necrosis factor (TNF), inflammation, and insulin resistance in the journal Science." (PMID 34030688, 2021). "TNF-α is a well-known proinflammatory cytokine, which functions as an important mediator of insulin resistance in PCOS." (PMID 34637688, 2021). "Another common denominator in the pathogenesis of insulin resistance, hypertension, and salt sensitivity (SS) is immune activation involving pro-inflammatory cytokines like tumor necrosis factor (TNF)-α, IL-1β, and IL-6." (PMID 34966295, 2021). "Diabetes occurs in part because the accumulation of activated innate immune cells in metabolic tissues leads to the release of inflammatory mediators, especially IL-1β and TNFα, which promote systemic insulin resistance and β-cell damage." (PMID 33936349, 2021). "TNF-α and IL-6 are involved in the disruption of insulin signalling and the further stimulation of gene expression related to insulin resistance." (PMID 34658643, 2021). "Elevated levels of IL-6 and TNF-α also induce insulin resistance and promote the development of CHD." (PMID 34824593, 2021). "TNF induced insulin resistance in adipocytes by inhibiting insulin-induced IRS1 tyrosine phosphorylation and insulin-induced glucose uptake and played a role in angiogenesis by inducing VEGF production synergistically with IL-1B and IL-6." (PMID 34306139, 2021). "Studies also reported that the inhibition of TNFα and IL-6 prevented the development of insulin resistance in obese animals." (PMID 34869524, 2021). "Other methods were used in this study to induce insulin resistance in 3T3L1 adipocytes such as treatment with high insulin, dexamethasone, and TNFα." (PMID 33498179, 2021). "After that, the levels of glucose and insulin in serum, HOMA-IR as an indicator of insulin resistance, the ocular level of oxidative markers, TNF-α, IL-1β, MIPs, and MCP-1 along with ocular gene expression of NF-κB, Nrf2, and miR-146a-5p were evaluated." (PMID 34804425, 2021). "In this study the relationship between lipid metabolite, lipid-based insulin resistance, and hepatocyte functionality indexes and tumor necrosis factor alpha (TNF-α) with extracellular heat shock protein 70 (eHsp70) was investigated." (PMID 35050141, 2021).